WNT5A (Wnt family member 5A)
Diseases named in the same sentence as WNT5A in open-access papers (continued):
Sharing a sentence is not in itself a finding about the gene and the disease.
diabetes (20 papers, 2015 to 2026). "This diabetes-associated epigenetic change translated into a dramatic reduction of Wnt-5a levels in diabetic ex vivo corneas and cultured LEC." (PMID 37460827, 2023). "Moreover, Wnt5a is secreted by macrophages, which are involved in the production of different pro-inflammatory cytokines and have been associated with chronic low-grade inflammation in adipose tissue and type 2 diabetes mellitus." (PMID 32491086, 2020). "In summary, although elevating Wnt5a in a hyperglycemic state can increase BMD, this alone is insufficient to fully assess the risk of fracture in individuals with diabetes." (PMID 37106471, 2023). "As an important cytokine secreted by adipose tissue, Wnt5a has attracted the attention of researchers in research related to diabetes." (PMID 37255814, 2023). "As one of the important cytokines secreted by adipose tissue, the research on Wnt5a and diabetes has attracted the attention of the majority of researchers." (PMID 37255814, 2023). "Briefly, endothelial cells from patients with diabetes mellitus revealed 1.3-fold higher Wnt5a levels (P = 0.01) along with 1.4-fold higher JNK activation (p < 0.01), without reporting a substantial difference in total JNK levels." (PMID 36984870, 2023). "In patients with diabetes mellitus, insulin administration promoted inhibition of Wnt5a and JNK signaling while the addition of A23187 resulted in eNOS activation by enhancing nitric oxide production in endothelial cells." (PMID 36984870, 2023). "In this sense, although WNT5A has lipogenic effects, it has been reported that the inhibition of its pathway in the pancreas can lead to diabetes, which agrees with our results." (PMID 36077270, 2022). "We excluded the factors about smoke and diabetes and found serum Wnt5a and Wnt11 levels positively correlated to E/e′ (Wnt5a: r = 0.455, p = 0.010; Wnt11: r = 0.480, p = 0.006)." (PMID 34564708, 2021). "Understanding the mechanism by which stellate cells regulate islet function via Wnt5a can help us classify crosstalk between cells inside the islets and the pathogenesis of diabetes." (PMID 32184820, 2020). "The aim of this study was to determine the correlation between serum Wnt5a and Sfrp5 concentrations and glomerular filtration rate in patients with type 2 diabetes mellitus and chronic kidney disease." (PMID 32491086, 2020). "The GFR of each individual was estimated and the serum Sfrp5 and Wnt5a levels were subsequently quantified to determine the correlation of these proteins with the clinical evolution of CKD patients with type 2 diabetes mellitus." (PMID 32491086, 2020). "To date, research on the connections among the Wnt5a protein, Sfrp5, and diabetes has mainly focused on adipose tissue, inflammation, and insulin resistance." (PMID 32184820, 2020). "The mechanisms leading to ISCs quiescence play an important role in regulating islet function via the Wnt5a-Fzd5 system and can help us understand the crosstalk between cells inside the islets of Langerhans and serve as a target for the prevention of diabetes." (PMID 32184820, 2020). "In comparisons of serum Wnt5a concentration between healthy people and patients with type 2 diabetes mellitus, it has been reported that diabetic patients have higher serum Wnt5a concentration than that of control individuals." (PMID 32491086, 2020). "Previous studies of Wnt5a and diabetes focused on islet development, insulin resistance, inflammation, and studies relating the Wnt5a antagonist protein Sfrp5 to islet function." (PMID 32184820, 2020). "It is important to mention that our study was the first to find a correlation between serum Wnt5a levels and glomerular filtration rate in patients with type 2 diabetes mellitus." (PMID 32491086, 2020). "Interesting, serum wnt5a was gradually increased in patients with long-term diabetes and kidney disease compared to patients with T2DM and onset DKD." (PMID 31890678, 2019).
diabetes (continued). "Research on the connections between the Wnt5a protein, Sfrp5, and diabetes is mainly concentrated on adipose tissue, inflammation, and IR." (PMID 31097962, 2019). "Serum wnt5a was gradually increased in long-term diabetes patients with kidney disease compared to T2DM with onset DKD patients." (PMID 31890678, 2019). "The many causes of endothelial dysfunction have been linked to key hallmarks of diabetes such as oxidative stress, insulin resistance, ROCK activation, and proinflammatory signaling of Wnt5a." (PMID 29928236, 2018). "Animal studies have demonstrated that Wnt5a is an important player in insulin resistance and diabetes." (PMID 27608847, 2016). "Myeloid-restricted Wnt5a overexpression mice further confirmed the positive role of macrophage-derived Wnt5a in insulin resistance and diabetes." (PMID 27608847, 2016). "In conclusion, we report that Wnt5a levels correlated with the duration of diabetes." (PMID 31890678, 2019). "We speculated that the Wnt5a protein might regulate islet function and be involved in the onset of diabetes as a protective factor." (PMID 31890678, 2019). "The decreased wnt5a level observed in patients with onset T2DM in this study may suggest that changes in the wnt5a level represent a regulatory mechanism to counteract metabolic stress and β cell dysfunction in diabetes." (PMID 31890678, 2019). "We speculate that the Wnt5a protein may regulate islet function and be involved in the onset of diabetes as protective factors." (PMID 31890678, 2019). "Future studies with greater sample size will be needed to assess whether a direct connection between diabetes and WNT5A expression in VAT exists in humans, as suggested by our previous mouse studies." (PMID 29229927, 2017). "Wnt5a protein may play different roles in different stages of diabetes." (PMID 37255814, 2023). "Therefore, Wnt5a might play an important role in the development of type 2 diabetes mellitus and its renal complications." (PMID 31890678, 2019). "The study also included 282 human subjects with type 2 diabetes mellitus who were analyzed by measuring circulating levels of SFRP5 and WNT5A and brachial-ankle pulse wave velocity." (PMID 36984870, 2023). "Our recent clinical study showed that Wnt5a levels were significantly downregulated in patients with newly diagnosed T2DM and gradually increased in long-term diabetes patients with kidney disease." (PMID 32184820, 2020). "The diabetes group had significantly lower PPAR-γ and Wnt5a levels than the healthy group, but had higher SREBP-1cand ER levels." (PMID 31993389, 2019). "The subjects in the diabetes group had higher triglycerides (TG), total cholesterol (TC), NP, ER, SREBP-1c, Wnt5a, FBG, and TG levels than the healthy group, but lower levels of low-density lipoprotein cholesterol (LDL-C) and PPAR-γ than the healthy group." (PMID 31993389, 2019). "Our recent clinical study showed that Wnt5a levels were significantly downregulated in patients with newly diagnosed T2DM and gradually increased in long-term patients with diabetes with kidney disease." (PMID 31097962, 2019). "We aim to investigate the circulating Wnt5a levels in in different clinical stages of T2DM and evaluate its correlation of duration of diabetes mellitus chronic complication." (PMID 31890678, 2019). "Wnt5a is markedly upregulated in visceral adipose tissue (VAT) and correlates strongly with indices of inflammation and diabetes mellitus." (PMID 28724439, 2017). "Study groups included 42 patients with type 2 diabetes mellitus, 43 non-diabetic controls, and evaluation of human aortic endothelial cell function isolated and treated with Wnt5a." (PMID 36984870, 2023). "The noncanonical pathway mediated by the Wnt5a protein can affect the occurrence of diabetes by inhibiting fat formation and obesity through the inhibition of PPARγ and C/EBP in preadipocytes." (PMID 32184820, 2020).
diabetes (continued). "Overall, these findings indicate that WNT5A signaling regulation is critical for pancreatic progenitor development and its inhibition partially rescues the GLI2P>L HET defects that may ultimately contribute to diabetes onset." (PMID 38509065, 2024). "Similarly, Wnt-5a treatment of wounded diabetic organ-cultured corneas reduced healing time by 37% (p<0.05) vs BSA treatment (control), with acquisition of normal-like patterns of LESC markers K15 and K17, and diabetes-suppressed integrin α3β1 and nidogen-1." (PMID 37460827, 2023). "And the presence of CHD was associated with plasma WNT5A (positive) concentrations, plasma SFRP5 (negative) concentrations and plasma WNT5A/SFRP5 ratio (positive) independently of traditional risk factors (hypertension, hyperlipidemia, diabetes and smoking)." (PMID 32004418, 2020). "Some of our data suggest that the contribution of non-canonical WNT5A signaling to IL-6 production and inflammation may be particularly relevant in subjects with diabetes, which typically exhibit high levels of systemic inflammation." (PMID 29229927, 2017). "In addition, WNT5A expression levels in VAT correlated with those of some of the PCP signaling components, such as VANGL2, PRICKLE1, DSH1,2,3 and DIVERSIN/ANKRD6 only in subjects with diabetes." (PMID 29229927, 2017). "The connection between WNT5A expression in VAT and IL-6/CRP levels is of particular relevance, given the large body of clinical evidence that links increased IL-6 signaling and/or increased circulating CRP levels to insulin resistance, diabetes and atherosclerotic CVD4,40–43." (PMID 29229927, 2017). "However, there are no studies of Wnt-5a in systemic corneal diseases such as diabetes." (PMID 37460827, 2023). "With the exception of WNT5A, the increased expression of PCP genes in VAT was not affected by gender or diabetes status (data not shown)." (PMID 29229927, 2017). "Results revealed that non-canonical Wnt5a signaling and JNK activity correlated with vascular reluctance to insulin action and to induce endothelial dysfunction, thus offering a novel therapeutic opportunity to protect the vasculature in patients with diabetes mellitus." (PMID 36984870, 2023). "Similarly, Wnt-5a level was decreased by 60% (p<0.05) in diabetic vs non-diabetic LEC by ELISA (Full Moon Biosystems), definitively confirming suppression of Wnt-5a in diabetes." (PMID 37460827, 2023).
glioblastoma (20 papers, 2013 to 2026). The most malignant astrocytic tumor (WHO grade IV). "The study objective was to evaluate the potential prognostic significance of WNT5A genes as diagnostic biomarkers for various types of cancer, such as glioblastoma (GMB), lung squamous cell carcinoma (LUSC), and lung adenocarcinoma (LUAD)." (PMID 39176352, 2024). "WNT5A overexpression was associated with an invasive phenotype of human glioblastoma, and particularly with stem-like features in the mesenchymal subtype." (PMID 33799999, 2021). "For example, Wnt5a was found to be associated with decreased overall survival in patients with glioblastoma, which was considered to have oncogenic potential." (PMID 32268875, 2020). "For example, MALAT-1 induces EMT in various cancers via the Wnt/β-catenin signalling pathway, while loss of WIF1 enhances the migratory potential of glioblastoma cells through WNT5A activation mediated by MALAT1." (PMID 29701689, 2018). "WIF1 reduced glioblastoma migration in vivo and in vitro by inhibiting the Wnt5a/p38-MAPK/Ca2+ pathway." (PMID 39687904, 2024). "Meanwhile, down-regulation of WIF1 has been shown to enhance the migratory aptitude of glioblastoma via WNT5A that induces expression of MALAT1." (PMID 34178658, 2021). "The importance of Wnt signaling in recurrence was also demonstrated in glioblastoma, where epigenetic activation of WNT5A expression was shown to contribute to tumor recurrence by promoting differentiation of glioblastoma stem cells into endothelial cells." (PMID 34446021, 2021). "In glioblastoma, miR-129-5p represses Wnt5a expression and blocks the protein kinase C (PKC)/extracellular signal-regulated kinase (ERK)/nuclear factor (NF)-κB and c-Jun N-terminal kinase (JNK) pathways." (PMID 34660566, 2021). "Clinically, high ROR1 and WNT5A expression correlates with poor glioblastoma prognosis, and WNT5A may serve as a circulating biomarker." (PMID 41562250, 2026). "In recurrent glioblastoma (GBM) patients, the methylation levels of the promoters and genes of Wnt5a, β-catenin and Wnt3a are lower in comparison with the primary GBM patients." (PMID 38886806, 2024). "Many of the genes identified through this meta-analysis have in fact been implicated in development of astrocytoma including EGFR (amplification occurs in ∼40% of primary glioblastomas, HIF-1α, MYC, WNT5A, and IDH3A." (PMID 23737970, 2013). "Indeed, rhSFRP2 decreased RhoA activity induced by Wnt5A in both U251 and T98MG cells (glioblastoma)." (PMID 38802858, 2024). "Further, we collected experimentally validated genes that could contribute to the invasive ability of glioblastoma cells (such as ZEB1, HNRNPC, WNT5A, and DRAM1) to evaluate the invasive scores for each cell (see section “Materials and Methods”)." (PMID 33505440, 2020). "In addition, overexpression of miR-129-5p also inhibits Wnt5a expression and blocks protein kinase C (PKC)/ERK/NF-κB and JNK pathways, thereby inhibiting the proliferation of glioblastoma cells." (PMID 31624237, 2019).
liver fibrosis (20 papers, 2012 to 2026). "In contrast, SFRP5 deficiency exacerbated CCl4‐induced liver fibrosis by enhancing Wnt5a–JNK signaling." (PMID 41541657, 2026). "Studies in liver fibrosis indicate that in vitro, Notum reduced the Wnt5a-induced pJNK activity in hepatic cells." (PMID 40271154, 2025). "In liver fibrosis, several studies have identified a functional role of Wnt5a in the fibrogenesis process." (PMID 41183564, 2025). "In particular, Wnt5a is involved in the liver degeneration, being overexpressed in liver fibrosis, which presents FZD2 and FZD7 as receptor." (PMID 35334792, 2022). "As a pro-inflammatory cytokine, higher Wnt5a expression was found in animal models of liver fibrosis and its profibrotic properties were primarily regulated by the profibrogenic mediator TGF-β and activation of hepatic stellate cells." (PMID 34371968, 2021). "Inhibition of Wnt5a/Fz2 signaling by Sfrp5 and subsequent hepatic stellate cells inactivation, mitigated mouse liver fibrosis." (PMID 34371968, 2021). "Our study found that the expression of Wnt genes (Wnt1, Wnt2, Wnt3, Wnt3a and Wnt5a) was upregulated, and Wnt pathway signalling in hepatocytes was active during the progression of schistosomiasis-induced liver fibrosis." (PMID 28331224, 2017). "Both genes are players in different Wnt signaling pathways and during in vitro activation of HSC as well as during liver fibrosis an increased Wnt5a expression has been reported." (PMID 26065684, 2015). "To seek an explanation for the effect of Wnt1 or Wnt5a on liver fibrosis, we knockdown Wnt1 and Wnt5a in HSC-T6 cells by siRNA transfection." (PMID 26537990, 2015). "Wnt4 is known to contribute to renal fibrosis, and Wnt3a and Wnt5a are involved in lung and liver fibrosis respectively." (PMID 24747916, 2014). "In HBV‐induced liver fibrosis, Notum downregulation of Wnt5a signaling exerts antifibrotic effects." (PMID 41541657, 2026). "The expression of Wnt5a in myofibroblasts was reported to be induced by the profibrotic factor TGFβ, playing a crucial role in the regulation of fibrotic matrix proteins induced by TGFβ in the context of liver fibrosis." (PMID 38532410, 2024). "In addition, it reduces liver fibrosis through Wnt5a/Fz2 signaling, while also acting protectively on the pancreas." (PMID 34371968, 2021). "Determining the degree to which HSC-derived Wnt5a is required to maintain these intercellular signalling networks and its functional contribution to liver fibrosis will be important to discover but will require genetic studies in which Wnt5a expression is selectively deleted in HSC." (PMID 26566235, 2015). "The data warrant detailed investigation of Wnt5a in liver fibrosis." (PMID 26566235, 2015). "Thus, upregulated Wnt1 and Wnt5a in MCD diet-induced steatofibrosis mice may account for the steatohepatitis-related liver fibrosis in the present study." (PMID 32461992, 2020). "Briefly, lncRNA SNHG1 silencing was observed to downregulate SMURF1 by upregulating miR-15a, diminishing ubiquitination of UVRAG to activate ATG5/Wnt5a axis, which accelerated HLC differentiation from BMSCs and repressed liver fibrosis to inhibit cirrhosis." (PMID 35194023, 2022). "Another study showed that WNT-5A, a ligand for Wnt signaling, regulated TGF-β levels and controlled its profibrotic activities in liver fibrosis." (PMID 33442383, 2020). "Thus, modulation of Wnt5a is a potential target to mitigate the biliary EMT process and decelerate progression of liver fibrosis." (PMID 41183564, 2025). "Augmented levels of WNT-5A are also detected in the dermal fibroblasts from keloids, whereas WNT-5A expression is identified in the fibrotic areas of affected human liver and found increased in liver tissues from mouse model of liver fibrosis." (PMID 26514730, 2016). "We observed that CM414 abrogated the effects of TGFβ1 on the expression of WNT-5A, a prominent growth factor of the non-canonical WNT pathway involved in liver fibrosis and TGFβ1-mediated HSC activation." (PMID 33322158, 2020).
liver fibrosis (continued). "WNT-5A is a WNT family member that activates the non-canonical WNT pathways, and importantly it plays a relevant role in TGFβ1 mediated HSC activation and liver fibrosis." (PMID 33322158, 2020).